SLC7A11 (solute carrier family 7 member 11)
Diseases named in the same sentence as SLC7A11 in open-access papers (continued):
Sharing a sentence is not in itself a finding about the gene and the disease.
lung cancer (continued). "This interaction leads to the regulation of SLC7A11 expression by RBMS1 through EIF3D, consequently inhibiting ferroptosis and promoting the progression of lung cancer." (PMID 38654320, 2024). "Activated CD8+ T cells release interferon-gamma, down-regulate the expression of SLC7A11 and SLC3A2, and inhibit the uptake of cystine by lung cancer cells to achieve anti-tumor effects." (PMID 38562175, 2024). "Since HPV16 was detected in only eight lung carcinomas from Chile, we randomly selected 24 cases from 196 HPV-negative cases showing information regarding smoking habits for subsequent SLC7A11 analysis and comparisons." (PMID 39769017, 2024). "Given that SLC7A11 emerged from in silico data, we analyzed a sub-cohort of 32 lung carcinomas from Chilean patients (24 HPV-negative and 8 HPV-positive) to assess SLC7A11 gene expression." (PMID 39769017, 2024). "According to the current research content, the targets of ferroptosis in lung cancer mainly focus on the regulation of antioxidant pathways, among which GPX4 and SLC7A11 are the core targets of the GSH-dependent antioxidant pathway." (PMID 37005430, 2023). "At the same time, SFN can also inhibit the expression of SLC7A11, leading to the decrease of GSH and the increase of ROS level in lung cancer cells." (PMID 37005430, 2023). "In the ferroptosis related studies of lung cancer, CAP can inhibit the proliferation of A549 and NCI-H23 cells and induce ferroptosis by inactivating SLC7A11/GPX4 signaling pathway." (PMID 37005430, 2023). "The expression of some proteins of the ferroptosis pathway (SLC7A11 and ACSL3) was also decreased after insufficient RFA of lung cancer cells." (PMID 37948404, 2023). "In the case of lung cancer cells, RBMS1 inhibits SLC7A11 expression, thereby reducing SLC7A11-mediated cystine uptake and facilitating ferroptosis in lung cancer cells." (PMID 37728413, 2023). "More importantly, RBMS1 is also identified to modulate the evasion of ferroptosis during lung cancer progression through interacting with the translation initiation factor eIF3d directly to bridge the 3’- and 5’ UTR of SLC7A11." (PMID 36989117, 2023). "Knocking down RBMS1 suppressed the translation of SLC7A11 and reduced SLC7A11C-mediated cystine uptake and eventually facilitated ferroptosis and sensitized radioresistant lung cancer cells to radiotherapy." (PMID 36989117, 2023). "Small ubiquitin-like modifier (SUMO) specific protease 1(SENP1) can regulate A20 by desumoylation, and then inhibit ferroptosis of lung cancer cells by affecting the interaction between A20 and ACSL4, SLC7A11." (PMID 37005430, 2023). "In the field of lung cancer, the regulatory axis of LncRNA T-UCR Uc.339/miR-339/SLC7A11 was discovered for the first time, and its regulatory effects and mechanisms on lung adenocarcinoma metastasis were explored in vivo and in vitro." (PMID 35399708, 2022). "Tumors with higher SOX2 expression are more resistant to ferroptosis, and the expression of SLC7A11 is positively correlated with SOX2 in mouse and human lung cancer tissues." (PMID 36105219, 2022). "After knockout of KEAP1 in lung cancer cells, the authors found upregulation of NRF2 and SLC7A11 expectedly, but the GPX4 level even decreased in these lung cancer cell lines." (PMID 36264074, 2022). "For example, SLC7A11 provides resistance to BRAF and MEK inhibitors in BRAFV600E mutant melanoma, geldanamycin resistance in lung cancer, cisplatin resistance in gastric cancer, temozolomide resistance in glioma and gemcitabine resistance in pancreatic cancer." (PMID 35280777, 2022). "The results showed that SLC7A11 was higher in CRC, esophageal cancer, head and neck cancer, kidney cancer, liver cancer, lung cancer, pancreatic cancer, and uterus cancer, and lower in lymphoma and ovarian cancer." (PMID 34722530, 2021). "Our study found that both SLC7A11 and GPX4 were overexpressed in CRC, and SLC7A11 was highly expressed in lung cancer by analyzing TIMER and Oncomine databases." (PMID 34722530, 2021).
lung cancer (continued). "Activation of NFE2L2 negatively regulates ferroptosis in various cells (including lung cancer cells) by upregulating various target genes, e.g. heme oxygenase 1 (HMOX1), SLC7A11, GPX4, and superoxide dismutase 2 (SOD2)." (PMID 34742351, 2021). "For instance, PGK1 promotes glycolysis-driven aggressiveness in gastric and colorectal cancers; P4HA1 regulates collagen remodeling and hypoxia adaptation in breast and lung cancers; and SLC7A11/xCT contributes to ferroptosis resistance in pancreatic, glioma, and prostate cancer models." (PMID 41562911, 2025). "Our findings suggest that targeting SLC7A11 through engineered BEVs presents a promising approach to inhibit NSCLC progression while activating ferroptosis, offering insights into novel therapeutic strategies against lung cancer." (PMID 41030277, 2025). "Contrary to observations in lung cancer 65, where YTHDC2 was reported to diminish SLC7A11 expression through reduced SLC7A11 mRNA stability, our findings reveal that YTHDC2 facilitates the upregulation of SLC7A11 expression by enhancing its translational efficiency in the epileptic condition." (PMID 39310099, 2024). "In this study, we found increased survival in HPV-negative and SLC7A11-negative patients with lung cancer." (PMID 39769017, 2024). "As a key regulator of ferroptosis, the inhibition of SLC7A11 translation can induce ferroptosis, and when the SLC7A11 is upregulated, ferroptosis is inhibited, which is not conducive to lung cancer treatment." (PMID 39400975, 2024). "Consistently, we observed the positive correlation between ELF3 and SLC7A11 expression only in human lung cancer tumors with the PTEN low expression, not in the whole patient population." (PMID 39695109, 2024). "The impact of SLC7A11 and SLC3A2 on the prognosis of lung cancer have been documented, it is still uncertain whether NCKAP1 and GYS1 influence the prognosis in lung cancer remains unclear." (PMID 38223725, 2024). "Thus, we found that SLC7A11/xCT is frequently up-regulated in both smokers and HPV16-positive lung cancer patients." (PMID 39769017, 2024). "The interaction of HMMR with SLC7A11 activates ferroptosis, enhances the cytotoxic effect of CD8 +T cells, and regulates the tumor immune microenvironment, suggesting an interaction with SLC7A5 in lung cancer." (PMID 39228892, 2024). "In contrast to these genes, SOX2 plays a role in the repression of ferroptosis, as indicated by the evidence that SOX2 enhanced the resistance of lung cancer cells to ferroptosis by maintaining the level of SLC7A11 and regulating cysteine metabolism and GSH level in lung cancer cells." (PMID 38509680, 2024). "In addition, silencing SLC7A11 expression reduces ROS and MDA accumulation, resulting in ferroptosis in non–small-cell lung cancer." (PMID 37433225, 2023). "And circ P4HB could regulate SLC7A11 by regulating miR-1184 to trigger GSH synthesis, which can protect lung cancer cells from erastin-induced ferroptosis, and promote tumor growth in vivo." (PMID 37005430, 2023). "They found that SLC7A11 and GPX4 are dysregulated in many types of cancers and may serve as candidate prognostic biomarkers, such as colorectal cancer and lung cancer." (PMID 37807410, 2023). "Likewise, a similar relationship was observed between RNA binding protein RBMS1 and SLC7A11, in a way that depletion of RBMS1 sensitizes lung cancer cells to ferroptosis and radiotherapy." (PMID 34926310, 2021). "Likewise, KEAP1-mutant lung cancer cells were shown to have higher levels of NRF2 and its downstream target SLC7A11." (PMID 34926310, 2021). "A number of the markers in this study had previously been reported as expressed as mRNA or protein in lung cancer: CAIX, CAXII, KK-LC-1, desmoglein 3, GPR87, Ly6/PLAUR domain-containing protein 3 and solute carrier family 7 member 11 protein." (PMID 29371917, 2017).
lung cancer (continued). "This might have been due to the low basal expression of SLC7A11 in both MC38 cells cocultured with adipocytes and the tumor tissue of obese mice, in contrast to previous reports showing that HFD could exacerbate lung cancer progression by upregulating SLC7A11." (PMID 40141120, 2025). "Butyrate can induce direct binding of ATF3 to the SLC7A11 promoter, thereby modulating the ATF3/SLC7A11 pathway, up-regulating ATF3 expression and decreasing SLC7A11 expression in lung cancer cells and activating erastin-induced iron death in lung cancer cells." (PMID 40520902, 2025). "In summary, further study of the expression of m6A methylation-related molecules in lung cancer cells and the mechanism of ferroptosis regulation by m6A methylation-related molecules such as SLC7A11 and GPX4 may provide a new feasible pathway for the regulation of ferroptosis in lung cancer." (PMID 38515565, 2024). "Furthermore, we found decreased survival in HPV/SLC7A11-positive patients with lung cancer when compared to HPV/SLC7A11-negative cases." (PMID 39769017, 2024). "To determine whether the regulation of SLC7A11 by SNF2L is consistent across different cancer cells, we disrupted SNF2L expression in HT-1080 fibrosarcoma cells, Huh-7 liver cancer cells and H1299 lung cancer cells." (PMID 39532848, 2024). "Indeed, SLC7A11 transcripts were more frequently detected in smokers than in non-smokers with lung carcinoma (p = 0.0498)." (PMID 39769017, 2024). "Moreover, high SLC7A11 levels increased cystine absorption, promoted GSH synthesis, increased GPX4 activity, enhanced the antioxidant capacity of lung cancer cells, inhibited lung cancer cell ferroptosis, and promoted cancer development." (PMID 37056388, 2023). "In lung cancer, AKR1B1 is a STAT3 activator that promotes glutathione de novo synthesis, eliminates ROS, protects cell from death, and reduces EGFR TKI drug sensitivity by upregulating the cystine transporter SLC7A11, it would be a therapeutic target for dealing with EGFR TKI resistance." (PMID 36512456, 2023). "Dihydroartemisinin (DHA) inhibits lung cancer cell proliferation and colony formation, enhances cell death, and induces ferroptosis by inactivating the polypeptide 2 (PRIM2)/SLC7A11 axis, indicating that the inhibitory expression of PRIM2 may be a potential therapeutic target for lung cancer." (PMID 34630843, 2021). "Moreover, overexpression of xCT (SLC7A11), a cystine/glutamate antiporter has been recently found to regulate glucose metabolism and intracellular GSH/GSSG redox balance as well as mediate progression of lung cancer." (PMID 30413072, 2018). "For example, HIF-1α could promote ferroptosis by regulating SLC7A11 in hepatic stellate cell or HMOX1 in Leydig and Sertoli cell of testes, and it also was reported to inhibit ferroptosis by activating the Hippo‐YAP signaling pathway in non‐small cell lung cancer or lncRNA-PMAN in gastric cancer." (PMID 37415103, 2023). "We made similar observations in another KEAP1 WT lung cancer cell line H23 cells: KEAP1 deletion rendered H23 cells resistant to ferroptosis induced by erastin, RSL3, but not FIN56; SLC7A11 knockdown promoted RSL3- or ML162-induced ferroptosis in H23 cells but not in KEAP1 KO counterparts." (PMID 35459868, 2022).
hepatocellular carcinoma (141 papers, 2016 to 2026). A malignant tumor that arises from hepatocytes. "For example, a four-gene signature (ABCB6, FLVCR1, SLC48A1, and SLC7A11) was created to build diagnostic and prognostic models for hepatocellular carcinoma (HCC)." (PMID 40002678, 2025). "The authors proved that aspirin caused ferroptosis by inhibiting NF-κB p65-activated SLC7A11 transcription, whereas NF-κB p65 overexpression interfered with the aspirin-induced ferroptosis of hepatocellular carcinoma cells." (PMID 38539832, 2024). "High expression of SLC7A11 is significantly associated with poor differentiation and a more advanced stage of hepatocellular carcinoma and is an independent prognostic factor for survival." (PMID 37940859, 2023). "SLC7A11 expression is positively associated with HIF-1α in human hepatocellular carcinoma (HCC) tissues." (PMID 35624785, 2022). "Higher levels of SLC7A11 are associated with poor differentiation and advanced disease stage in hepatocellular carcinoma (HCC)." (PMID 35280777, 2022). "One previous study also suggested that the pharmacological inhibition of USP8 can induce ferroptosis and inhibit the progression of hepatocellular carcinoma by decreasing the stability of the O-GlcNAcylation of solute carrier family 7 member 11 (SLC7A11)." (PMID 40136417, 2025). "AKR1C3, which plays a role in steroid metabolism and prostaglandin synthesis, has been shown to regulate ferroptosis in hepatocellular carcinoma (HCC) through the YAP/SLC7A11 signaling pathway." (PMID 39897029, 2025). "For example, lncRNA PMAN inhibits ferroptosis in gastric cancer by up-regulating SLC7A11, whereas lncRNA HEPFAL promotes ferroptosis in hepatocellular carcinoma by down-regulating SLC7A11." (PMID 40628711, 2025). "In liver cancer, DHA induces hepatocyte ferroptosis by inhibiting ATF4, SLC7A11 or xCT, and also induces ferroptosis in hepatocellular carcinoma by promoting PEBP1/15-LO formation." (PMID 40994946, 2025). "Macrophage‐derived SLC7A11 significantly reduces ferroptosis activity, promoting TAMs recruitment, infiltration, and M2 polarization, which accelerates hepatocellular carcinoma development and metastasis." (PMID 41438182, 2025). "capitata, which induces ferroptosis in hepatocellular carcinoma cells by downregulating SLC7A11 and promoting GPX4 degradation." (PMID 40790027, 2025). "Sorafenib, an FDA-approved ferroptosis inducer for hepatocellular carcinoma, demonstrated great treatment effect in inhibiting SLC7A11." (PMID 40855044, 2025). "This downregulates the transcriptional expression of SLC7A11 (also known as xCT, the cystine/glutamate antiporter), promoting lipid peroxidation and inducing ferroptosis in hepatocellular carcinoma cells." (PMID 40830338, 2025). "KIAA1429, a key component of the m6A methyltransferase complex, targets SLC7A11 during ferroptosis in Hepatocellular carcinoma (HCC) cells." (PMID 38550378, 2024). "Both in vivo and in vitro studies have shown that Lico A promotes ferroptosis in hepatocellular carcinoma cells by suppressing SLC7A11 expression." (PMID 39040097, 2024). "For example, the disulfidptosis-related gene SLC7A11 is proposed to potentially emerge as a new prognostic biomarker for hepatocellular carcinoma (HCC), presenting opportunities for developing personalized cancer immunotherapy strategies." (PMID 39701955, 2024). "It has been reported that lncRNA HEPFAL accelerates ferroptosis in hepatocellular carcinoma by regulating SLC7A11 ubiquitination." (PMID 39194582, 2024). "Consistently, WB analysis was used to measure SLC7A11 expression in hepatocellular carcinoma tissues at the protein level." (PMID 38397869, 2024). "A previous literature documented that SOCS2 can enhance SLC7A11 ubiquitination to mediate ferroptosis of hepatocellular carcinoma cells." (PMID 38267746, 2024). "YAP/TAZ 121 and C8orf7648 act as negative regulators of ferroptosis by upregulating SLC7A11 transcription, thus driving resistance to sorafenib in hepatocellular carcinoma." (PMID 38993573, 2024).
hepatocellular carcinoma (continued). "According to these results, siRNA-SLC7A11 reduced the expression of SLC7A11 in four hepatocellular carcinoma cell lines." (PMID 38397869, 2024). "Hepatocellular carcinoma tissues (referred to as T) showed higher levels of SLC7A11 protein than paired normal adjacent tissues (referred to as N)." (PMID 38397869, 2024). "Significantly higher expression of SLC7A11 mRNA in hepatocellular carcinoma tissues was confirmed by RT-qPCR analysis." (PMID 38397869, 2024). "Additionally, SOCS2 can promote the K48-linked ubiquitination and degradation of SLC7A11 to facilitate ferroptosis of hepatocellular carcinoma (HCC) cells, thus affecting the radiosensitivity and prognosis of this cancer." (PMID 38267746, 2024). "Collectively, these findings highlight that SLC7A11 inhibition substantially curtails the proliferation, migration, and invasion capabilities of hepatocellular carcinoma cell lines." (PMID 38397869, 2024). "In conclusion, our study underscores the therapeutic potential of targeting SLC7A11 in tandem with RFA to bolster antitumor immunity in hepatocellular carcinoma." (PMID 39742309, 2024). "Scutellaria barbata reduced GPX4 and SLC7A11 mRNA and protein levels to induce ferroptosis characterized by iron-mediated lipid peroxidation and ROS metabolism in hepatocellular carcinoma, thus suppressing HCC tumorigenicity in vivo." (PMID 39021832, 2024). "Saikosaponin A (SsA) induces ferroptosis in hepatocellular carcinoma (HCC) cells by inhibiting SLC7A11 and activating ATF3 through endoplasmic reticulum stress, highlighting its potential as a therapeutic ferroptosis inducer in HCC treatment." (PMID 39315094, 2024). "Stress responses accompany hepatocyte injury, as seen in the ATF4-dependent SLC7A11 expression in a NASH-related hepatocellular carcinoma mouse model." (PMID 38844964, 2024). "Gallic acid inhibit SLC7A11 and Wnt/β-catenin signaling to promote hepatocellular carcinoma ferroptosis." (PMID 38738174, 2024). "Disulfidptosis, a regulated form of cell death, has been recently reported in cancers characterized by high SLC7A11 expression, including invasive breast carcinoma, lung adenocarcinoma, and hepatocellular carcinoma." (PMID 38962013, 2024). "Inhibition of USP8, by stabilizing OGT and impacting cystine uptake via SLC7A11, effectively suppresses hepatocellular carcinoma progression and induces ferroptosis, suggesting its potential as a therapeutic target for HCC treatment." (PMID 39315094, 2024). "The cystine/glutamate antiporter solute carrier family 7 member 11 (SLC7A11) is a novel prognostic biomarker for hepatic carcinoma." (PMID 34336819, 2021). "In NASH, the expression of SLC7A11 was reported to be up-regulated in human hepatoma cells with a positive correlation to the expression of lipid-associated genes." (PMID 33152221, 2021). "Consistent with this study, previous studies have reported that sorafenib-induced hepatoma cell death is primarily dependent on triggering ferroptosis by inhibiting SLC7A11/xCT10,11,24." (PMID 33931597, 2021). "Additionally, lncRNA HEPFAL can promote the ubiquitination of SLC7A11, reducing its stability and inducing ferroptosis in hepatocellular carcinoma cells, which can also impact the function of macrophages in the tumor microenvironment." (PMID 40191204, 2025). "Furthermore, lncRNA HEPFAL promotes the ubiquitination of SLC7A11, reducing its stability and inducing ferroptosis in hepatocellular carcinoma cells." (PMID 40191204, 2025). "Overall, the results clearly validated the possibility that SLC7A11 could be a good target for hepatocellular carcinoma treatment in certain situations." (PMID 38397869, 2024). "The effects of SLC7A11 on malignant biological behaviors of hepatocellular carcinoma cell lines were then examined by CCK8, which include healing, colony formation, and transwell migration assays, for the reason that cell migration and invasion are the initial stages of metastasis." (PMID 38397869, 2024).